STAT3 (signal transducer and activator of transcription 3)
Diseases named in the same sentence as STAT3 in open-access papers (continued):
Sharing a sentence is not in itself a finding about the gene and the disease.
tumor (continued). "FOLR1 can internalize folates into the cells, which is crucial to DNA repair and synthesis, and mediate the activation of pro-oncogene STAT3, which contributes to angiogenesis, tumor proliferation, and metastasis." (PMID 34124126, 2021). "AP-2α, a central member of the AP-2 family, can function as a tumour suppressor to block the IL-6/Jak2/STAT3 signalling pathway." (PMID 34425834, 2021). "Intriguingly, the presence of phosphorylated-STAT3+ immunosuppressive astrocytes is promoted by tumor and microglia cells." (PMID 34690699, 2021). "For example, sphingosine-1-phosphate, which is produced from sphingosine, increases cell proliferation and tumor malignancy by activating both signal transducer and activator of transcription 3 (STAT3) and the Warburg effect." (PMID 34775964, 2021). "Mechanistic investigations demonstrated that the miR-197-mediated CKS1B/STAT3 axis was excavated exerting tumor progression regulated by various protooncogenes like BCL2 Apoptosis Regulator (BCL2), MYC, and Cyclin D1(CCND1)." (PMID 34925510, 2021). "Targeting STAT3 also became an immune therapeutic strategy, which can modulate tumor-mediated immune suppression." (PMID 34961815, 2021). "Overall, the tumour‐derived S‐type cells prevented apoptosis in the N‐type cells via ALK‐independent STAT3 activation triggered by secreted factors." (PMID 33932101, 2021). "STAT3 has been related to oncogenic or tumor-suppressive roles in GBM depending on the tumor genotype." (PMID 33762015, 2021). "Their results showed that PCBP1 regulates the alternative splicing of STAT3 exon 23 to promote the transformation of oncogenic subtype STAT3α to the tumour suppressor subtype STAT3β14." (PMID 34857818, 2021). "Coupled with the observation that the STAT3 pathway also induces tumor growth, angiogenesis, and metastasis, several STAT3 inhibitors are in development to treat solid malignancies." (PMID 33807608, 2021). "In the setting of GBM, STAT3 inhibition has demonstrated preclinical efficacy with respect to decreasing tumor cell proliferation, migration, and invasion." (PMID 34483843, 2021). "IL6/JAK/STAT3 signaling promotes tumor proliferation, invasiveness, and metastasis and suppresses antitumor immune response in the TME." (PMID 33790966, 2021). "PTEN-deficient tumor xenografts were established in nude mice that were treated with PI3K/AKT/mTOR and/or STAT3 inhibitors." (PMID 33431808, 2021). "Collectively, we propose a model in which bufalin reduces the expression of angiogenic genes by inhibiting the phosphorylation of STAT3 on endothelial cells, thereby antagonizing the proangiogenic effects of the tumour microenvironment." (PMID 34496870, 2021). "miR-204-5p is a tumor suppressor in HNSCCs, which inhibits tumor growth, metastasis, and stemness by suppressing the signal transducer and activator of transcription 3 (STAT3) signaling and EMT via targeting SNAI2, SUZ12, HDAC1, and JAK2." (PMID 33917482, 2021). "Studies have demonstrated that STAT3 undergoes constitutive phosphorylation at Tyr-705 (STAT3Y705) by autocrine or paracrine signaling in the tumor microenvironment." (PMID 35053027, 2021). "Hyperactivation of STAT3 is important in the microenvironmental formation of inflammatory tumors and promotes tumor proliferation and metastasis." (PMID 34976809, 2021). "Increased IL-6 in TME will trigger hyperactivation of downstream JAK/STAT3 signaling to drive proliferation, angiogenesis, and metastasis of tumor cells 13-16." (PMID 34093869, 2021). "The overexpression of PD-1/PD-L1 in tumor cells is significantly related to the phosphorylation of STAT3." (PMID 34326876, 2021). "It is reported that the abnormal activation of STAT3 promotes in tumor formation, while STAT1’s abnormal activation in tumors triggers the body's anti‐tumor mechanism." (PMID 33377624, 2021). "Mechanistically, IL-6 mediated the activation of pro-survival signals, especially the JAK/STAT3 signaling pathway, to facilitate tumor growth and distant metastasis." (PMID 34657635, 2021).
tumor (continued). "STAT3 is a well-known tumor therapeutic target, and our previous studies have demonstrated that STAT3 is also highly expressed in OS and showed apoptosis-associated effects, We investigated whether the STAT3 pathway is involved in CQ action in OS cells and xenograft tumor samples." (PMID 34170850, 2021). "In the TIME, the abnormal activation of the JAK/STAT3 signaling contributes to an immunosuppressive tumor microenvironment, which promotes tumor growth and metastasis." (PMID 34326840, 2021). "IL-6/STAT3 pathway suppression, β-catenin suppression, pSmad3C/P21 tumour-signalling suppression, and CD57+ NK recruitment are said to be the underlying mechanisms for the action of IL-37." (PMID 34336101, 2021). "It is well known that JAK/STAT3 pathway is considered as one of the most promising new targets for cancer therapy due to its role in tumor cell proliferation, survival, invasion and immunosuppression." (PMID 34408811, 2021). "By synchronous installation of IL-2 receptor and binding site for the transcription factor STAT3 to the endodomain, vigorous JAK–STAT3/5 cytokine, cascade can be instigated in local tumor environment and thus minimizes systemic inflammation." (PMID 33673696, 2021). "In turn, these cells perpetuate an immunosuppressive tumor microenvironment via a feedforward loop through the secretion of pro-tumorigenic factors that sustain STAT3 activation within tumor cells." (PMID 34944848, 2021). "CSCs mainly influence the immune cells around the tumor through the Notch-NF-κB axis, HH, Wnt and STAT3 pathways to create ITAIMs." (PMID 34179009, 2021). "The phosphorylation of STAT3 can promote the proliferation of tumor cells, in which phosphatases such as Src homology-2-containing protein tyrosine phosphatase 1 (SHP-1), SHP-2, SOCS1, SOCS3, and PTP1B can induce the dephosphorylation." (PMID 34195079, 2021). "STAT3 plays a central role in neutrophil biology by regulating the production of inflammatory cytokines (e.g., IL1, IFNγ, TNF), while STAT3 inhibition in neutrophils enhances their cytolytic activity and promotes tumor regression." (PMID 34944848, 2021). "Hyperactivation of STAT3 enhances the expression of its target genes, which promote tumor cell migration and proliferation." (PMID 33535185, 2021). "STAT3 directly regulates the expression of oncogenes and triggers tumor progression and also induces tumor-induced immunosuppression that indirectly promotes human cancer growth." (PMID 34489925, 2021). "In conclusion, this study identified STAT3/CDK2/4/6 as an oncogenic prognosticator of cancer-associated fibroblasts and tumor immune infiltrations, and poor prognosis of multiple cancer cohorts." (PMID 33668805, 2021). "It has been shown that tumor cells dependent on long-term STAT3 signaling are more sensitive to STAT3 inhibitors than normal cells." (PMID 34733856, 2021). "Further in vivo experiments confirmed that the combination of circUBE2Q2 knockdown and STAT3 inhibitors inhibited tumor growth more significantly than knocking down circUBE2Q2 alone." (PMID 34611143, 2021). "SH2 superbinder has been verified to block the LIFR/STAT3 pathway and interrupt the tumor progression." (PMID 33783993, 2021). "Tumor invasion and metastasis are under the regulation of STAT3 by different mechanisms such as; induction of transcription of matrix-degrading enzymes such as matrix metalloproteinase and activation of epithelial to mesenchymal transition (EMT)." (PMID 33672756, 2021). "CAF-intrinsic STAT3 activity within the TME correlates with tumor progression, immune suppression and eventually the establishment of metastases." (PMID 34858425, 2021). "Recently, the PAI‐1/PIAS3/Stat3/miR‐34a axis has been reported to regulate tumour metastasis in NSCLC." (PMID 33932101, 2021). "The IL6/JAK/STAT3/SIGNALING pathway was considered as a potential mechanism of genomic instability to influence tumor progression." (PMID 34712264, 2021).
tumor (continued). "Mechanistically, STAT3 upregulates V-ATPase expression while blockade of STAT3 activity repressed V-ATPase expression in these tumor cells as well as sensitized cells to anoikis, increased ROS production, and misfolded protein accumulation." (PMID 34234852, 2021). "Taken together, it is important that appropriate in vitro assays and murine models are employed to study CAFs in tumor development as well as understanding the influence STAT3 has on CAF functionality." (PMID 34858425, 2021). "Mechanistically, we found that AhR expression contributed to the secretion of Interleukin-6 (IL-6), thereby promoting tumor cells proliferation through the STAT3 and NF-kB/TIM4 signals." (PMID 34657635, 2021). "In conclusion, we found that combination treatment of stattic and circUBE2Q2 silencing has a stronger synergistic effect on tumor suppression in vivo through the STAT3 signaling pathway." (PMID 34611143, 2021). "Various kinds of gene mutation are the radical reason of tumor generation and IL-6/JAK/STAT3 aggravate the influence by promoting excessive gene expression." (PMID 33390844, 2021). "Due to a positive correlation between STAT3 and the survival of tumour cells in response to cisplatin, JAK-STAT signalling, which induces apoptosis through IFNs and cisplatin, is an important pathway for cancer cell killing." (PMID 34631119, 2021). "IL-6 that is produced by TAM also promotes tumor cells proliferation and invasive potential via STAT3 signaling." (PMID 33418996, 2021). "Overexpression and continuous activation of STAT3 can upregulate the anti-apoptotic protein (Bcl-2) to inhibit the apoptosis of tumor cells and prolong the cell life cycle." (PMID 34493692, 2021). "Previous studies showed that G3BP1 participated in the epithelial-mesenchymal transition process via modulating Wnt/β-catenin, Smad, and STAT3 signaling to promote tumor progression and metastasis." (PMID 33726799, 2021). "The co-option of reactive astrocytes of the tumor microenvironment by means of STAT3 signaling fosters the implantation and survival of metastasis by modulating the immune system." (PMID 34067120, 2021). "STAT3 is known to affect tumor growth and invasion and the JAK/STAT3 pathway is activated in various cancer types." (PMID 34336660, 2021). "Accordingly, ablating Stat3 with small-molecule inhibitors induces NK cell- and T cell-dependent tumor growth inhibition." (PMID 33987190, 2021). "Altogether, these findings highlight how STAT3 signaling can impart an immunomodulatory effect in CAFs during tumor development." (PMID 34858425, 2021). "Hepatocyte-specific inhibition of STAT3 has been shown to inhibit tumor growth in a mouse model of chemically induced HCC." (PMID 34557407, 2021). "IFNβ repressed STAT3 activity in tumor-infiltrating IFNβKO neutrophils resulting in anti-angiogenic and anti-tumor effects." (PMID 34572138, 2021). "What is more, hyperactivation of STAT3 is found to regulate the immune microenvironment of the tumor." (PMID 34938816, 2021). "Apart from these advantages, STAT3 inhibition was recently proposed to improve innate and adaptive anti-tumor immunity and immune surveillance." (PMID 33957948, 2021). "IL-6 is overexpressed in a variety of cancers, and it can activate the STAT3 signaling pathway to promote tumor occurrence." (PMID 34976805, 2021). "CAFs enhance the metastatic potential of human NSCLC cells through a IL6/STAT3 signaling pathway, which in turn promotes tumor angiogenesis through the upregulation of VEGF and bFGF." (PMID 34944848, 2021). "Overexpression of NFIB in GBM cells induces cell differentiation and inhibits tumor growth via signal transducer and activator of transcription 3 (STAT3) signaling mechanisms." (PMID 34012965, 2021).
tumor (continued). "As a very important member of the STAT family, STAT3 has been shown to be involved in cancer cell proliferation, metastasis, and angiogenesis in multiple reports, and STAT3 regulates tumour angiogenesis by regulating VEGF and HIF-1α." (PMID 33865381, 2021). "To further address the role of CREPT in STAT3-induced tumours, we transformed NIH3T3 fibroblasts using v-Src, which constitutively induces STAT3 phosphorylation, in the presence of stably expressed HA-CREPT." (PMID 33531691, 2021). "We unveiled L1CAM as a master regulator of OCSC pathophysiology through a previously unrecognized L1CAM/FGFR/SRC/STAT3 signaling pathway, thus shedding light on novel molecular mechanisms that sustain the tumor-supporting function of OCSC." (PMID 34645505, 2021). "Targeting IL6/STAT3 axis represents a promising therapeutic strategy to counteract the tumor growth and invasion." (PMID 34576335, 2021). "In melanoma, gastric, lung, liver and prostate cancers, tumor-infiltrating B cells can persistently express VEGF (vascular endothelial growth factor) and other pro-angiogenic genes via STAT3 signaling, fostering tumor progression by increasing angiogenesis." (PMID 34164398, 2021). "Accumulating evidence reveals that STAT3 is phosphorylated for tumor progression and inflammation, immunosuppression and immune escape." (PMID 34440920, 2021). "Of note, the role of this protein in tumor progression has been extensively studied and several types of cancers are characterized by high levels of STAT3 protein and its persistent activation." (PMID 34440160, 2021). "Signal transducer and activator of transcription 3 (STAT3) is constitutively activated in both tumor and immune cells, representing a promising target for cancer therapy." (PMID 34489925, 2021). "Another interesting finding was the involvement of the NEAT1/miR-183/STAT3 axis in the MET process, which is the opposite process of the EMT and was proposed as a crucial mechanism underlying the formation of metastatic tumours." (PMID 33546665, 2021). "Another strategy is to use BV6 along with inhibition of signal transducer and activator of transcription 3 (STAT3), which is an important factor in the survival of tumor cells, and NIK as a mediator of BV6 unpredicted side effects." (PMID 34502560, 2021). "Treatments with either monomer or dimerized PS-acet.-STAT3 peptides significantly reduced tumor growth." (PMID 33491667, 2021). "A mouse liver metastatic tumor model showed that STAT3 inhibition enhanced the anti-tumor efficacy of CAR-T therapy by activating apoptotic signaling pathways and decreasing proliferative signaling pathways in liver-associated MDSCs." (PMID 34336860, 2021). "Previous reports demonstrated that the inhibition of the STAT3 increases the radiation sensitivity of tumor cells, thus mediating radiation-induced apoptosis in different cell lines." (PMID 35052553, 2021). "STAT3 and STAT5 are associated with tumor genesis and progression, and STAT3, in particular, is closely associated with tumor cell survival, immunosuppression, and persistent inflammation." (PMID 34539403, 2021). "The studies performed on several tumor models have demonstrated that the upregulation of PD-L1 is regulated by the IL-6/STAT3 signaling pathway." (PMID 34829995, 2021). "The anti-proliferative/apoptotic activity of nintedanib on tumor cells seems to occur, at least in part, through the negative regulation of the signal transducer and activator of transcription 3 (STAT3)." (PMID 34439322, 2021). "STAT3 has been recognized by gene expression profiling of PCa CSCs to regulate the stem cell niche and tumor initiation." (PMID 34638338, 2021). "Specifically, several molecules have been demonstrated to promote tumor metastasis by activating the STAT3 signaling pathway." (PMID 34789307, 2021). "Related to this, several regulators have been reported to mediate the activation of STAT3, including IL-6, which in fact can be produced by tumor cells." (PMID 34638305, 2021).
tumor (continued). "Mechanistically, LRG1 exerts its function by regulating EGFR/STAT3 signalling, a central pathway involved in tumour metastasis." (PMID 34208965, 2021). "TAMs preferentially secrete TGF-β to stimulate CSC-like properties by inducing EMT, while TAM-derived IL-6 induces CD44+ HCC stem cell expansion by activating STAT3, thus promoting tumor development through CSC growth." (PMID 34235155, 2021). "EGFR is a membrane-bound receptor tyrosine kinase protein that activates downstream intracellular signaling pathways, including MAPK (RAS/RAF/MEK/ERK), PI3K/AKT, and JAK/STAT3 signaling, and plays a role in tumor cell growth, proliferation and differentiation." (PMID 34925375, 2021). "STAT3 participates in many of the widely active carcinogenic signaling as well as the transcriptional modulation of different tumor-promoting factors." (PMID 34368156, 2021). "The STAT3 protein is widely present in a variety of tumor tissue, affecting many biological behaviors of tumor cells, and acting as an oncogene, while JAK is responsible for the activation of STAT." (PMID 34900984, 2021). "More importantly, we determined the expression of phosphorylated STAT3 and NF-kB in tumor tissues from patients, and an additional increase of p-STAT3 was found in H-S tumor tissues." (PMID 34657635, 2021). "STAT3 contributes to immunosuppression in the tumor microenvironment by the induction of immunosuppressive cytokines production in cancer cells, including IL-6, IL-8 and VEGF." (PMID 34360552, 2021). "STAT1 always plays opposite roles to STAT3 in tumorigenesis and mostly triggers antiproliferative and pro-apoptotic responses while enhancing anti-tumor immunity." (PMID 34746227, 2021). "Tumor-derived exosomes were also shown to contain several other activating components of the STAT-3 pathway, including HSP70 and HSP72, which can induce the development of MDSCs." (PMID 34078376, 2021). "Clinical observations also support the tumor suppressor role of STAT3 in head and neck cancer and breast cancer." (PMID 33670049, 2021). "ETBF promotes the production of IL-17 b y Th17 cells through the rapid activation of the STAT3 pathway, which further promotes the activation of the NF-κB and Wnt pathways and the production of intestinal inflammatory tumor microenvironment." (PMID 33959032, 2021). "Extracellular KrasG12D in tumor-derived exosomes directly promotes alternatively activated or M2-like macrophage polarization via signal transducer and activator of transcription 3 (STAT3)-dependent fatty acid oxidation." (PMID 34290984, 2021). "The inhibition of STAT3 activity also increases the antitumor T cell-mediated immune response, leading to apoptosis of tumor cells and inhibition of tumor growth or even tumor regression." (PMID 33525658, 2021). "Among all the tumour samples examined, positive p‐STAT3 staining was identified in 36 tumour samples (76.5%)." (PMID 33410581, 2021). "In both studies the activation of STAT-3 was shown to lead to the increased tumour growth, angiogenesis and EMT as well as an immunosuppressive TME in mice in the latter study." (PMID 34439879, 2021). "Overproduction of IL-6 by tumor cells activates STAT-3, a key transcription factor central to immune escape and it is an important regulator in the crosstalk between tumor cells and TME." (PMID 35059436, 2021). "In osteosarcoma, it decreases the mRNA levels of some tumor angiogenic genes, such as VE-cadherin and integrin β3 and suppresses STAT3 phosphorylation so as to potently impede cell migration and invasion." (PMID 35046810, 2021). "Blocking the STAT-3 pathway in tumor cells results in tumor-specific T cell responses due to the increase in the expression of pro-inflammatory cytokines and chemokines." (PMID 33407613, 2021). "Persistent STAT3 activation promotes cell-cycle progression, tumor invasion, metastasis, and angiogenesis." (PMID 33431808, 2021).